BTBD3 (BTB domain containing 3)
Description:
Acts as a key regulator of dendritic field orientation during development of sensory cortex. Also directs dendrites toward active axon terminals when ectopically expressed (By similarity).
Synonyms: KIAA0952; dJ742J24.1
Tractability: PROTAC: ubiquitination databases record sites on it.
Gene: Protein-coding gene on chromosome 20 (11,890,723 to 11,926,609, forward strand). Ensembl gene ENSG00000132640.
Subcellular location: Cytoplasm, cytosol; Nucleus
Subcellular location (Human Protein Atlas): Vesicles
Gene Ontology:
Molecular function: identical protein binding; protein binding
Biological process: cerebral cortex development; dendrite morphogenesis; neurogenesis
Cellular component: cytosol; nucleus
Genetic constraint (gnomAD): Loss-of-function variants: 14 observed, 41.53 expected, observed/expected ratio (o/e) 0.34, 90% interval 0.22 to 0.53. The upper end of that interval is the gene's LOEUF score, 0.53, which puts it in group 2 of 6, group 1 being the genes least tolerant of losing a copy. Missense variants: 422 observed, 685 expected, observed/expected ratio (o/e) 0.62, 90% interval 0.57 to 0.67. Synonymous variants: 249 observed, 245.98 expected, observed/expected ratio (o/e) 1.01, 90% interval 0.91 to 1.12.
Homologues: Orthologues: chimpanzee BTBD3 (99% identical), guinea pig BTBD3 (98% identical), pig BTBD3 (98% identical), rat Btbd3 (98% identical), macaque BTBD3 (97% identical), rabbit BTBD3 (96% identical), dog BTBD3 (94% identical), tropical clawed frog btbd3 (91% identical), zebrafish btbd3b (88% identical), mouse Btbd3 (87% identical), Drosophila melanogaster lute (60% identical), Drosophila melanogaster CG17068 (28% identical), and 2 more. Paralogues in human: BTBD6 (68% identical), BTBD2 (40% identical), BTBD1 (38% identical), ABTB2 (21% identical), BTBD9 (20% identical), ABTB3 (19% identical), KBTBD4 (19% identical), ABTB1 (14% identical), SPOPL (13% identical), SPOP (13% identical), KLHL11 (10% identical).
Diseases named in the same sentence as BTBD3 in open-access papers:
BTBD3 is named in the same sentence as 16 diseases in open-access papers, as found by Europe PMC text mining. Sharing a sentence is not in itself a finding about the gene and the disease. The quoted sentences say what the papers report.
Alagille syndrome (1 paper, 2020). "Duplication of JAG1, BTBD3, and FLRT3, or ASXL1 induces Alagille syndrome, neurological dysfunction or chromatin remodeling." (PMID 32684981, 2020).
Anxiety (1 paper, 2019). Intense feelings of nervousness, tension, or panic often arise in response to interpersonal stresses. "Interestingly, anxiety-like and depression-like behaviors were unaltered in Btbd3 HT and KO mice." (PMID 31501410, 2019). "Thus, Btbd3 mice were assessed for anxiety-like and depression-like behaviors." (PMID 31501410, 2019). "In contrast, Btbd3 expression did not alter anxiety-like, depression-like, or sensorimotor behaviors." (PMID 31501410, 2019). "Thus, our findings suggest that the behavioral phenotypes observed in Btbd3 KO mice are not modulated by anxiety-like or depression-like states." (PMID 31501410, 2019).
cutaneous malignant melanoma (1 paper, 2020). "Molecular mechanisms by which INPPL1 and BTBD3 affect melanoma progression require further investigation as well as their potential therapeutic value in order to block the metastatic dissemination of cutaneous malignant melanoma." (PMID 32179834, 2020).
lymph node metastasis (1 paper, 2020). "More importantly, INPPL1 correlates with the development of distant and lymph node metastasis and, both, INPPL1 and BTBD3, with the development of any type of metastasis." (PMID 32179834, 2020). "BTBD3 and ATF4 were found not to be significantly up-regulated with regard to the development of distant or lymph node metastasis (p 0.079 and p 0.119, respectively)." (PMID 32179834, 2020).
melanoma (1 paper, 2020). A malignant, usually aggressive tumor composed of atypical, neoplastic melanocytes. "In this regard, not only INPPL1 but both, INPPL1 and BTBD3 expression were significantly higher in primary melanomas that developed any type of metastasis (p < 0.001 and p 0.021, respectively)." (PMID 32179834, 2020). "INPPL1 and BTBD3 were downregulated when melanoma cells expressed miR-205, indicating that these genes are potential miR-205 targets." (PMID 32179834, 2020). "miR-205, INPPL1, BTBD3 and ATF4 expression was measured by RT-qPCR in human primary melanoma tissue samples." (PMID 32179834, 2020). "Among INPPL1 and BTBD3, INPPL1 was found to be the most clinically relevant gene that seems to be mediator of miR-205 suppression of melanoma progression." (PMID 32179834, 2020). "INPPL1 and BTBD3 expression was significantly higher in ulcerated than in non-ulcerated primary melanomas (p < 0.001 in both cases)." (PMID 32179834, 2020). "In contrast, BTBD3 inhibition did not imply a reduction of the invasion ability of melanoma cells." (PMID 32179834, 2020).
meningioma (1 paper, 2014). A generally slow growing tumor attached to the dura mater. "BTBD3, LOC339535, and TBC1D9 genes were present in both lists, and thus are potentially important in meningioma pathogenesis." (PMID 25003081, 2014).
obsessive-compulsive disorder (1 paper, 2019). A disorder characterized by the presence of persistent and recurrent irrational thoughts (obsessions), resulting in marked anxiety and repetitive excessive behaviors (compulsions) as a way to try to decrease that anxiety. "BTB/POZ domain-containing 3 (BTBD3) was identified as a potential risk gene in the first genome-wide association study of obsessive-compulsive disorder (OCD)." (PMID 31501410, 2019).
cancer (2 papers, 2020 to 2025). A tumor composed of atypical neoplastic, often pleomorphic cells that invade other tissues. "At present, there are limited studies on BTB/POZ Domain-Containing Protein 3 (BTBD3) involvement in cancer." (PMID 32179834, 2020).
tumor (1 paper, 2020). "Additionally, we investigated the association of INPPL1, BTBD3 and ATF4 expression with histological tumor parameters such as Breslow thickness and ulceration as well as with patient gender and age at diagnosis." (PMID 32179834, 2020).
BTBD3 also shares sentences with these, for which no sentence is quoted: anorexia nervosa (1 paper); colorectal cancer (1); depression (1); hepatocellular carcinoma (1); osteoporosis (1); plasma cell disorders (1); psychiatric disorder (1).